MVK (mevalonate kinase)
Description:
Catalyzes the phosphorylation of mevalonate to mevalonate 5-phosphate, a key step in isoprenoid and cholesterol biosynthesis.
Synonyms: MK; LRBP; MVLK; POROK3
Tractability: Small molecule: it has a high-quality binding pocket. PROTAC: ubiquitination databases record sites on it; its protein half-life has been measured.
Gene: Protein-coding gene on chromosome 12 (109,573,255 to 109,598,125, forward strand). Ensembl gene ENSG00000110921.
Subcellular location: Cytoplasm; Peroxisome
Subcellular location (Human Protein Atlas): Cytosol; Vesicles
Pathways (Reactome):
Metabolism: Activation of gene expression by SREBF (SREBP); Lanosterol biosynthesis
Gene Ontology:
Molecular function: identical protein binding; mevalonate kinase activity; protein binding; ATP binding; magnesium ion binding
Biological process: cholesterol biosynthetic process; isoprenoid biosynthetic process; negative regulation of inflammatory response; isopentenyl diphosphate biosynthetic process, mevalonate pathway; farnesyl diphosphate biosynthetic process, mevalonate pathway; geranylgeranyl diphosphate biosynthetic process; sterol metabolic process; zymosterol biosynthetic process
Cellular component: cytoplasm; cytosol; peroxisome
Genetic constraint (gnomAD): Loss-of-function variants: 36 observed, 48.28 expected, observed/expected ratio (o/e) 0.75, 90% interval 0.57 to 0.99. The upper end of that interval is the gene's LOEUF score, 0.99, which puts it in group 4 of 6, group 1 being the genes least tolerant of losing a copy. Missense variants: 395 observed, 523.53 expected, observed/expected ratio (o/e) 0.75, 90% interval 0.69 to 0.82. Synonymous variants: 190 observed, 229.09 expected, observed/expected ratio (o/e) 0.83, 90% interval 0.74 to 0.94.
Gene-disease validity (ClinGen):
ClinGen rates the evidence that MVK causes each of these diseases.
mevalonate kinase deficiency (autosomal recessive): Definitive.
Homologues: Orthologues: chimpanzee MVK (99% identical), macaque MVK (91% identical), rabbit MVK (86% identical), dog MVK (85% identical), pig MVK (82% identical), rat Mvk (81% identical), mouse Mvk (81% identical), guinea pig MVK (79% identical), tropical clawed frog mvk (61% identical), zebrafish mvk (56% identical), Caenorhabditis elegans mvk-1 (39% identical), Drosophila melanogaster Mvk (32% identical). Paralogues in human: GALK1 (22% identical), GALK2 (19% identical).
Diseases named in the same sentence as MVK in open-access papers:
MVK is named in the same sentence as 108 diseases in open-access papers, as found by Europe PMC text mining. Sharing a sentence is not in itself a finding about the gene and the disease. The quoted sentences say what the papers report.
familial Mediterranean fever (34 papers, 2010 to 2025). Familial Mediterranean fever (FMF) is an autoinflammatory disorder characterized by recurrent short episodes of fever and serositis resulting in pain in the abdomen, chest, joints and muscles. "Differential diagnoses include scarlet fever, staphylococcal skin infections, toxic epidermal necrolysis, and recurrent fevers like familial Mediterranean fever or mevalonate kinase deficiency." (PMID 39262930, 2024). "The genetic study for Familial Mediterranean Fever, tumor necrosis factor receptor-associated periodic syndrome, Mevalonate kinase deficiency, showed the homozygous mutation p.M680I of exon 10 in MEFV." (PMID 31443670, 2019). "The ADDI is the first instrument to quantify damage in familial Mediterranean fever, cryopyrin-associated periodic syndromes, mevalonate kinase deficiency and tumour necrosis factor receptor-associated periodic syndrome." (PMID 30077992, 2018). "8/46 patients who had prominent fevers and/or systemic inflammation had testing for monogenic autoinflammation: mevalonate kinase deficiency (7/8), cryopyrin-associated periodic fever (4/8), familial Mediterranean fever (8/8) and NOD2 (1/8) mutations." (PMID 26833394, 2016). "The main diseases were adult-onset Still’s disease (AOSD), gout, systemic juvenile idiopathic arthritis, cryopyrin-associated periodic syndrome (CAPS), familial Mediterranean fever and mevalonate kinase deficiency." (PMID 25758134, 2015). "We searched for studies through the following words: “monogenic autoinflammatory disease”, “familial Mediterranean fever”, “mevalonate kinase deficiency”, “tumor necrosis factor receptor-associated periodic syndrome”, “cryopyrin-associated periodic syndrome”, and their synonyms." (PMID 32082075, 2019). "Included in this group are familial Mediterranean fever (FMF) and mevalonate kinase deficiencies (MKD; MIM#610377 for mevalonic aciduria and 260920 for hyper-IgD syndrome), all of which are recessively inherited." (PMID 21124859, 2010). "JIA: juvenile idiopathic arthritis, IBD: inflammatory bowel disease, FMF: familial Mediterranean fever, MVK: mevalonate kinase, JDM: juvenile dermatomyositis." (PMID 40018478, 2025). "Pyrin plays a role in inflammatory diseases such as Familial Mediterranean Fever (FMF), pyrin-associated autoinflammation with neutrophilic dermatosis (PAAND), and mevalonate kinase deficiency." (PMID 38660388, 2024). "Among SAIDs, the best-known include familial Mediterranean fever (FMF), cryopyrin-associated periodic syndrome (CAPS), and mevalonate kinase deficiency (MKD)." (PMID 36679996, 2023). "The cohort comprised 152 patients with familial Mediterranean fever (FMF; n = 71), cryopyrin-associated periodic syndromes (CAPS; n = 43), TNF-receptor associated periodic syndrome (TRAPS; n = 19), mevalonate kinase deficiency (MKD; n = 3) and unclassified AID (uAID; n = 16)." (PMID 37747561, 2024). "IL-1 blockade is also indicated for treatment of AIDs, such as cryopyrin-associated periodic syndromes (CAPS), familial Mediterranean fever (FMF), TNF receptor-associated periodic syndrome (TRAPS) and mevalonate kinase deficiency and in HLH/MAS." (PMID 40845184, 2025). "IL, interleukin; FMF, familial Mediterranean fever; MKD, mevalonate kinase deficiency; TRAPS, tumor necrosis factor receptor-associated periodic syndrome." (PMID 34858402, 2021). "Examples of monogenic SAIDs are Familial Mediterranean fever (FMF), cryopyrin associated periodic syndromes (CAPS), mevalonate kinase (MVK) deficiency and tumor necrosis factor receptor associated periodic syndrome (TRAPS)." (PMID 28381287, 2017). "In fact, pericarditis was noted in all 4 monogenic interleukin-1-mediated auto-inflammatory diseases including familial Mediterranean fever (FMF), cryopyrin-associated periodic syndrome (CAPS), TNF receptor-associated periodic syndrome (TRAPS), and mevalonate kinase deficiency (MKD)." (PMID 36232723, 2022).
familial Mediterranean fever (continued). "The antibody was approved in 2016 for three types of spontaneous inflammatory diseases: tumor necrosis factor receptor associated periodic syndrome (TRAPS), hyperimmunoglobulin D syndrome (HIDS)/mevalonate kinase (MKD), and familial Mediterranean fever (FMF)." (PMID 33362770, 2020). "Typical monogenic periodic fever syndromes include cryopyrin-associated periodic fever syndrome (CAPS), tumor necrosis factor receptor-associated periodic syndrome (TRAPS), mevalonate kinase deficiency/hyper IgD syndrome (MKD/HIDS), and familial Mediterranean fever (FMF)." (PMID 33603750, 2020).
mevalonic aciduria (24 papers, 2009 to 2025). Mevalonic aciduria (MVA) is a rare, very severe form of mevalonate kinase deficiency (MKD) characterized by dysmorphic features, failure to thrive, psychomotor delay, ocular involvement, hypotonia, progressive ataxia, myopathy, and recurrent inflammatory episodes. "Mevalonic aciduria (MA), the most severe form of mevalonate kinase deficiency, is an autosomal recessive disorder resulting from the deficiency of mevalonate kinase, an enzyme of the cholesterol and isoprenoid biosynthetic pathway." (PMID 39176373, 2024). "Mevalonic aciduria is a rare autosomal recessive disorder resulting from mevalonate kinase deficiency." (PMID 39176373, 2024). "Mevalonic aciduria is caused by homozygous or compound heterozygous MVK variants that affect enzyme function or expression more severely than p.V377I, and is associated with extremely low (<0.5%) or undetectable residual MK activity." (PMID 36189795, 2022). "Mutations in this gene lead to reduced mevalonate kinase activity varying from 0.5 to 28% as compared to that of healthy controls, the lowest being found in the most severe phenotype Mevalonic Aciduria." (PMID 35906690, 2022). "Mutations in the Mevalonate Kinase gene (MVK) are causes of a rare autoinflammatory disease: Mevalonate Kinase Deficiency and its more acute manifestation, Mevalonic Aciduria." (PMID 25663823, 2015). "Mutations in MVK are also responsible for the severe monogenic metabolic disorder mevalonic aciduria." (PMID 23547563, 2013). "Mevalonic aciduria, a rare autosomal recessive disease, represents the most severe form of the periodic fever, known as Mevalonate Kinase Deficiency." (PMID 24287904, 2013). "Mutations in the MVK gene can lead to hyperimmunoglobulinemia D syndrome and mevalonic aciduria." (PMID 39359475, 2024). "HIDS and mevalonic aciduria are two different phenotypes of mevalonate kinase (MVK) deficiency (MKD)." (PMID 38984133, 2024). "Mevalonate kinase deficiency and mevalonic aciduria (also known as hyper-IgD syndrome, or HIDS) are autosomal recessive diseases with similar genetic backgrounds to pathogenic MVK (mevalonate kinase) variants." (PMID 37759952, 2023). "Mutations in the MVK gene (12q24) encoding Mevalonate Kinase enzyme (MVK) cause Mevalonate Kinase Deficiency (MKD, OMIM #260920) and its more severe form, Mevalonic Aciduria (MA, OMIM #610377)." (PMID 25663823, 2015). "A mutation in the MVK gene can affect enzymatic activity of MVK and results in one of two distinct syndromes, HIDS or mevalonic aciduria." (PMID 19656398, 2009). "Pathogenesis of neuroinflammation in Mevalonate Kinase Deficiency and Mevalonic Aciduria has not yet been completely clarified, however different research groups have been suggesting the inflammasome complex as the key factor in the disease development." (PMID 25663823, 2015). "Recessive loss of function mutations in MVK can result in a spectrum of disease ranging from severe multisystem disease (mevalonic aciduria; MKD) to a milder autoinflammatory disease (HIDS)." (PMID 30766537, 2019). "MKD can be further broken down into two syndromes, Hyperimmunoglobulin D Syndrome (HIDS) and Mevalonic Aciduria (MVA), based on the residual amount of enzyme activity of mevalonate kinase." (PMID 31325964, 2019). "This insight suggests that pharmacological interventions aimed at stabilizing the MVK protein could offer potential therapeutic avenues for the treatment of MKD, especially for patients with severe forms such as mevalonic aciduria (MA)." (PMID 39600705, 2024). "A recessively inherited inflammosomopathy is mevalonate kinase deficiency (MKD), which causes attacks of variable severity ranging from the milder hyper-IgD syndrome (HIDS) to the most severe mevalonic aciduria (MA), considered as a continuous disease spectrum caused by mutations in the MVK gene." (PMID 33999387, 2021).
mevalonic aciduria (continued). "Mevalonate kinase deficiency, also known as hyperimmunoglobulinemia D syndrome (OMIM 260920) is characterized by an autosomal recessive Mendelian inheritance pattern and is allelic to another disorder, mevalonic aciduria (MA, OMIM 610377), characterized by a very low activity of the enzyme MVK." (PMID 28421071, 2017). "As there is no clear border between phenotypes, we will use the term mevalonate kinase deficiency, which encompasses both HIDS and mevalonate aciduria, to describe the disease in this paper." (PMID 25990874, 2015). "Mevalonic aciduria, an autosomal recessive disorder with complete absence of MVK activity, usually presents with a more severe clinical picture." (PMID 19656398, 2009).
hyperimmunoglobulinemia D syndrome (22 papers, 2006 to 2024). "The causative gene product of mevalonate kinase deficiency/hyper-IgD syndrome (MKD) (also known as hyper-IgD syndrome (HIDS)) is mevalonate kinase (MVK)." (PMID 34635190, 2021). "It results from a deficiency in mevalonate kinase (involved in the early steps of cholesterol biosynthesis), however a defect in mevalonate kinase can also result in hyperimmunoglobulinemia D syndrome." (PMID 33415129, 2020). "MVK is a key enzyme of the mevalonate/cholesterol pathway and biallelic hypomorphic mutations in MVK cause mevalonate kinase deficiency (MKD)/hyperimmunoglobulinemia D syndrome (HIDS)." (PMID 31456795, 2019). "In humans, when MVK mutations in homozygosity can give rise to hyperimmunoglobulinemia D syndrome, which the basic symptoms were fever and high concentrations of immunoglobulins D and A in blood." (PMID 29050287, 2017). "Two phenotypes of mevalonate kinase deficiency are known based on the level of enzymatic deficiency, mevalonic aciduria and hyperimmunoglobulinemia D syndrome, but a wide spectrum of intermediate phenotypes has been reported." (PMID 27012807, 2016). "Mevalonate kinase deficiency or hyper-IgD syndrome is a hereditary autoinflammatory syndrome caused by mutations in the mevalonate kinase gene." (PMID 25990874, 2015). "Hyperimmunoglobulinemia D syndrome is a rare autosomal recessive autoinflammatory disorder caused by mutations in the mevalonate kinase gene (MVK)." (PMID 23691418, 2013). "Mutation of mevalonate kinase (MVK) is thought to account for most cases of hyperimmunoglobulinemia D syndrome (HIDS) with recurrent fever." (PMID 22527518, 2012). "Mevalonic aciduria (MVA) and hyperimmunoglobulinemia D syndrome (HIDS) represent the two ends of a clinical spectrum of disease caused by deficiency of mevalonate kinase (MVK), the first committed enzyme of cholesterol biosynthesis." (PMID 16722536, 2006). "Furthermore, for the hyperimmunoglobulinemia D syndrome (HIDS)/mevalonate kinase deficiency (MKD) the MVK gene was described in 1999." (PMID 33401496, 2021). "MKD, also known as ‘hyper-IgD syndrome’ due to the common elevation of serum IgD found in these children, is caused by deficient or aberrant activity of mevalonate kinase, the second enzyme in the cholesterol biosynthesis pathway, as a consequence of mutations in the MVK gene." (PMID 35883675, 2022). "There are two forms of mevalonate kinase deficiency: mevalonic aciduria (MA), when residual function of the enzyme is undetectable (<1 % or <0.5 % according to different authors) and hyperimmunoglobulinemia D syndrome (HIDS), when residual function of the enzyme is 1.8–28 % (or 1–10 %)." (PMID 27012807, 2016). "Pyrin is also involved in the pathophysiology of hyperimmunoglobulinemia D syndrome (HIDS), a monogenic AID caused by MVK mutations." (PMID 36034552, 2022). "This was followed by the MVK, NLRP12, and IL36RN genes causing hyper IgD syndrome, (HIDS) and generalized pustular psoriasis (GPP) with 2 unique variants each, in 8 and 4 individuals, respectively." (PMID 34905135, 2021). "After FMF, other two AIDs were described: TNF-receptor associated periodic syndrome (TRAPS) and hyperimmunoglobulinemia D with periodic fever syndrome [hyper-IgD syndrome (HIDS)/mevalonate kinase (MVK)]." (PMID 28421071, 2017). "Hyper-IgD syndrome (HIDS) is one of the several autoinflammatory disorders and has an autosomal recessive mode of inheritance caused by pathogenic variants in the mevalonate kinase (MVK) gene." (PMID 32822427, 2020). "Also known as hyperimmunoglobulinemia D syndrome, MKD (OMIM 260920) is an autosomal recessive disease caused by mutations in the MVK gene, encoding for the enzyme mevalonate kinase, involved in the ATP-dependent phosphorylation of mevalonic acid into 5-phosphomevalonate." (PMID 24282415, 2013).
mevalonate kinase deficiency (17 papers, 2013 to 2025). "Mevalonate kinase deficiency (MKD) is a systemic autoinflammatory disease caused by biallelic mutations in MVK." (PMID 41585027, 2025). "Mevalonate kinase deficiency (MKD) is a monogenic SAID caused by biallelic mutations in MVK, which encodes a crucial metabolic enzyme of the mevalonate pathway." (PMID 41585027, 2025). "Mevalonate kinase deficiency (MKD) is an inherited autoinflammatory syndrome resulting from impaired isoprenoid biosynthesis due to biallelic mevalonate kinase (MVK) mutations." (PMID 41112284, 2025). "Strengths and limitations of mevalonate kinase enzyme and Rab prenylation assays for routine diagnostic workup of suspected mevalonate kinase deficiency (MKD)." (PMID 41585027, 2025). "Mevalonate kinase deficiency (MKD) is an autosomal recessive inherited disorder caused by mutations in the mevalonate kinase (MVK) gene on chromosome 12q24." (PMID 40038796, 2025). "In particular, human MVK has been well studied in relation to auto-immune diseases such as mevalonate kinase deficiency (MKD), and this led to the development and discovery of important drugs, such as anakinra and canakinumab." (PMID 35064110, 2022). "Mevalonate kinase deficiency (MKD) is a rare paediatric disease caused by mutations in the mevalonate kinase (MVK) gene and the accumulation of mevalonolactone (MEV) metabolites." (PMID 36555531, 2022). "Mevalonate kinase deficiency (MKD) is secondary to bi-allelic mutations of the gene coding for mevalonate kinase (MVK), an enzyme involved in the cholesterol biosynthesis." (PMID 35812440, 2022). "Mevalonate kinase deficiency (MKD) is a rare autoinflammatory condition caused by biallelic loss-of-function (LOF) mutations in mevalonate kinase (MVK) gene encoding the enzyme mevalonate kinase." (PMID 34809655, 2021). "Mevalonate kinase deficiency (MKD) is an autosomal recessive disease caused by loss-of-function mutations in the mevalonate kinase (MVK) gene." (PMID 32737687, 2020). "Mevalonate kinase deficiency (MKD), a rare auto-inflammatory disorder, arises from mutations in the MVK gene, disrupting isoprenoid biosynthesis, and affecting cellular processes." (PMID 39600705, 2024). "Mevalonate kinase deficiency (MKD) is a genetic SAID, a rare hereditary recurrent fever syndrome (HRF) caused by pathogenic variants in the mevalonate kinase (MVK) gene." (PMID 36788924, 2023). "Mevalonate kinase deficiency (MKD) is characterized by recurrent fevers and flares of systemic inflammation, caused by biallelic loss-of-function mutations in MVK." (PMID 36189795, 2022). "The last disease in this section is mevalonate kinase deficiency (MKD), which is an autosomal recessive disorder caused by mevalonate kinase gene (MVK) mutations." (PMID 33042144, 2020). "Mevalonate kinase deficiency (MKD) or HIDS is a periodic fever syndrome that is caused by LOF mutations in MVK, the gene that encodes mevalonate kinase (MVK), which is an enzyme in the cholesterol pathway." (PMID 32983099, 2020). "The rare autoinflammatory disease mevalonate kinase deficiency (MKD, which includes HIDS and mevalonic aciduria) is caused by recessive, pathogenic variants in the MVK gene encoding mevalonate kinase." (PMID 31474985, 2019). "A rare hereditary autoinflammatory disorder, involving the second enzyme in the mevalonate/cholesterol pathway, is mevalonate kinase deficiency (MKD), caused by mutations in the MVK gene encoding the enzyme mevalonate kinase." (PMID 24360083, 2013).